GRK4 (G protein-coupled receptor kinase 4)
Diseases named in the same sentence as GRK4 in open-access papers (continued):
Sharing a sentence is not in itself a finding about the gene and the disease.
Obesity (2 papers, 2015 to 2024). Accumulation of substantial excess body fat. "The obesity risk increased 7.06, 16.8, and 46.09-fold more in boys with GRK4 A486V, ACE, and SLC12A3 mutants as sodium intake increased." (PMID 25768006, 2015). "For examples, the GRK4 A486V mutant increased the obesity risk 1.75-fold more when the obesity index was used (P-trend = 0.015), however, the GRK4 A142V mutant decreased the obesity risk by 0.7-fold (P-trend = 0.05) when the WC was used (P-trend = 0.058)." (PMID 25768006, 2015). "The obesity risk increased with GRK4 A486V, ACE, and SLC12A3 variants in boys, whereas it increased with GRK4 A486V and CYP11B2 variants in girls as sodium intake increased." (PMID 25768006, 2015). "The obesity risk increased in the boys with the GRK4 A486V, ACE and SLC12A3 mutant and in girls with CYP11β-2 mutant and GRK4 A486V hetero type as they increased the residual-Na." (PMID 25768006, 2015). "Second, many research reported that the GRK4 A486V polymorphism affected the risk of obesity associated with sodium intake, according to how other genes were combined to GRK4 A486V variants." (PMID 25768006, 2015). "However, it was interesting to identify gender differences of the GRK4 A486V polymorphism on the risk of obesity, and observe that boys who carried mutant homozygotes showed high risks of obesity, while girls carrying heterozygotes, and not mutants, showed high risks of obesity." (PMID 25768006, 2015). "A high sodium intake markedly increased the obesity risk in variants of GRK4 A486V regardless of sex." (PMID 25768006, 2015). "In Korean children, the best combination to predict obesity was SLC12 A3, ACE and GRK4 A486V in boys, and CYP11β-2 and GRK4 A486V in girls as sodium intake was increased." (PMID 25768006, 2015). "For example, boys with GRK4 A486V, ACE, and SLC12A3 mutants and girls with GRK4 A486V hetero and CYP11β-2 mutant may reduce their daily sodium intake as if they want to reduce the prevalence of obesity." (PMID 25768006, 2015).
Cirrhosis (1 paper, 2022). A chronic disorder of the liver in which liver tissue becomes scarred and is partially replaced by regenerative nodules and fibrotic tissue resulting in loss of liver function. "Neither tumoral nor peritumoral GRK4 expression differed significantly between patients with high and low histopathological grade (p = 0.36), PVTT (p = 0.13), cirrhosis (p = 0.87), number of tumors (p = 0.95), or T stage (p = 0.372)." (PMID 35769816, 2022).
colorectal tumors (1 paper, 2022). "GRK4 was also found overexpressed in invasive breast cancer and frequently mutated in high microsatellite instability (MSI-H) colorectal tumors." (PMID 35769816, 2022).
diabetes (1 paper, 2024). "The impairment of the D1R function as part of the insulin resistance in type 2 diabetes mellitus in mice has also been related to increased GRK4 expression." (PMID 38961282, 2024).
granulosa cell tumor (1 paper, 2022). A slow-growing, malignant tumor, characterize by the presence of granulosa-like cells and Call-Exner bodies, that is almost always found in the ovary. "Two studies showed heterogenous expression for the differential GRK4 isoforms in human granulosa cell tumors and invasive breast cancer." (PMID 35769816, 2022).
liver cancer (1 paper, 2024). An epithelial or non-epithelial malignant neoplasm that arises from the liver. "Unlike the main location of GRK5 expression in the nuclear membrane, previous research has shown that the main location of GRK4 expression in HCC was cell plasma, although the detailed mechanism of GRK4 regulation of liver cancer remains to be elucidated." (PMID 38638965, 2024).
nicotine addiction (1 paper, 2022). "Three novel genes—SLC39A8, GRK4 and HGFAC—within loci associated with altered alcoholic drinks per week (ADW) or cigarettes per day (CPD) were selected to further study their role in alcohol and tobacco use disorder." (PMID 35661789, 2022).
renal fibrosis (1 paper, 2016). A final common manifestation of a wide variety of chronic kidney diseases characterized by glomerulosclerosis and tubulointerstitial fibrosis. "We also measured renal function and the effect on renal fibrosis after UTMD‐targeted GRK4 siRNA delivery to the kidneys in the SHRs." (PMID 27792639, 2016).
cancer (4 papers, 2021 to 2024). A tumor composed of atypical neoplastic, often pleomorphic cells that invade other tissues. "Among the downregulated DEGs, PLEKHA5, GRK4, MYRIP, and CD40 have established associations with various human cancers." (PMID 39911484, 2024). "Finally, the involvement of GRK4, PCYT2 and RGSL1 in cancer-related pathways and drug susceptibility needs further experimental validation." (PMID 34621245, 2021). "Finally, we analyzed the correlation between drug sensitivity of cancer cell lines in GDSC (Genomics of Drug Sensitivity in Cancer), and the GRK4, PCYT2 and RGSL1 expression levels." (PMID 34621245, 2021). "In addition, the nine mRNAs of the ceRNA regulatory networks included GRK4, PCYT2 and RGSL1, which showed prognostic relevance and was associated with cancer-related pathways such as DNA Damage, AR, ER, RASMAPK, and TSC-mTOR." (PMID 34621245, 2021). "However, the specific effects of GRK4 on cancer cells are unclear." (PMID 35769816, 2022).
cardiovascular disease (4 papers, 2012 to 2024). "Normotensive individuals with GRK4 polymorphisms show increased serum NT-proBNP concentration and may be at a greater risk of developing hypertension and cardiovascular disease." (PMID 22518293, 2012). "GRK4 may be a potential target to screen for the risk of future hypertension and cardiovascular disease so that lifestyle modifications such as salt restriction can be chosen by at-risk subjects to prevent future adverse events." (PMID 22518293, 2012). "Future research should focus on clarifying the specific regulatory pathways of GRK4 in oxidative stress and inflammatory responses through gene editing and molecular mechanism analysis and examining its cross-system impact in COPD and coexisting cardiovascular diseases." (PMID 39558015, 2024).
tumor (3 papers, 2021 to 2024). "We found that GRK4 is differentially expressed in HCC tumor tissues and low expression of GRK4 is associated with the poor prognosis." (PMID 35769816, 2022). "The low expression of GRK4 in tumor is associated with poor OS in HCC patients." (PMID 35769816, 2022). "Diverse GRK4 expression was seen in HCC tissues in the previous investigation, and individuals with HCC benefited from high GRK4 expression in the tumor." (PMID 38638965, 2024). "The average GRK4 intensity scores in tumor and peritumor in the training cohort were 1.1 and 2.5, respectively (p < 0.001), and those in the validation cohort were 1.1 and 2.3 (p < 0.001), respectively." (PMID 35769816, 2022). "We showed that an improving nomogram of tumoral GRK4 expression plus tumor type and T stage performed well with the AUCs of 0.82 in predicting the prognosis of HCC patients." (PMID 35769816, 2022). "In this study, distribution of the full-length GRK4 (GRK4α, referred as GRK4 in this manuscript) in tumor and peritumor tissues and its significance in the prognosis of patients with HCC were investigated." (PMID 35769816, 2022). "Tumoral GRK4 intensity, tumor type, and T stage were independent prognostic factors and used to form a nomogram for predicting overall survival (OS), which obtained a good concordance index of 0.82 and 0.77 in training and validation cohort, respectively." (PMID 35769816, 2022). "T stage, expression intensity of intratumoral GRK4, tumor type, tumor diameter, number of tumors, and presence of PVTT were associated with OS." (PMID 35769816, 2022). "In the present study, GRK4 inhibited the growth of HepG2 cells, which suggested that GRK4 might perform two heterogeneous functions in different types of tumor cells." (PMID 38638965, 2024). "The differential expression in peritumor and tumor tissues might suggest GRK4 a critical factor for OS in HCC patients." (PMID 35769816, 2022). "In addition, GRK4, PCYT2 and RGSL1A are potential TGCT-specific biomarkers that can predict RFS, tumor immunity and chemotherapeutic resistance." (PMID 34621245, 2021). "Interestingly, half of the patients with high GRK4 expression in the peritumor tissue displayed nonstaining in tumor tissues in the training cohort (p = 0.05)." (PMID 35769816, 2022).
Kidney Disease (2 papers, 2015 to 2022). "The therapeutic importance of the GRK4 single nucleotide polymorphisms (SNPs) was emphasised in the African American Study of Kidney Disease (AASK) where African-Americans with hypertensive nephrosclerosis were randomised to receive amlodipine, ramipril or metoprolol." (PMID 25775155, 2015). "Both the drugs are associated with the gene GRK4 and several studies have been published in literature supporting genetic variation in GRK4 gene and drug-induced hypertension and renal disorders." (PMID 35865963, 2022). "The therapeutic importance of the GRK4 SNPs was emphasised in the African American Study of Kidney Disease (AASK) where African-Americans with hypertensive nephrosclerosis were randomised to receive amlodipine, ramipril or metoprolol." (PMID 25775155, 2015).
GRK4 also shares sentences with these, for which no sentence is quoted: essential hypertension (8 papers); infection (2); atherosclerosis (1); Ellis-van Creveld syndrome (1); heart failure (1); Hyperinsulinemia (1); immune diseases (1); Insulin resistance (1); invasive breast carcinoma (1); melanoma (1); myocardial ischemia (1); nephrosclerosis (1); thyroid cancer (1).